IGF1 (insulin like growth factor 1)
Diseases named in the same sentence as IGF1 in open-access papers (continued):
Sharing a sentence is not in itself a finding about the gene and the disease.
Obesity (continued). "It was shown that levels of obesity-related inflammatory indicators (i.e. FFA, GSH-Px, IHNB, IL-1, IGF-1, and ROS) were statistically quite distinct among patients classified in different BMI groups (P<0.05)." (PMID 28515223, 2017). "One hypothesis that would be in line with our results is that obesity leads to increasing insulin levels and risk of hyperinsulinemia, which in turns decreases insulin-like growth factor (IGF) binding proteins, thus allowing increasing circulating levels of insulin-like growth factor I (IGF1)." (PMID 28954281, 2017). "In this model of diet-induced obesity (DIO), hypothalamic IGF1 expression was also significantly increased, compared to mice fed a standard chow diet (CD)." (PMID 29259155, 2017). "It was also observed that insulin, insulin-like growth factor 1 (IGF1), and IL-17 increased in obesity." (PMID 28387721, 2017). "The exact mechanisms of the relationship between IGF-1 and HDL-C in obesity are not fully understood at present." (PMID 27343122, 2016). "We, along with others have shown that a high-fat diet induces obesity and metabolic abnormalities typical of DM2, elevated glucose, insulin and IGF-1 in these strains." (PMID 26641266, 2015). "However, it is possible that the association of obesity with BMD is based in the conversion of androgen to estrogen, which improves bone mass in both males and females and maintains healthy plasma levels of insulin and regulating factors such as insulin-like growth factor-1, leptin, and adiponectin." (PMID 26090818, 2015). "Study the possible relationship of miR-27a, miR-27b, miR-143 and miR-145 with leptin, leptin receptors, IGF1 and IL10 is important to try to understand the changes that occur in obesity and its physiopathology." (PMID 24690978, 2014). "Levels of IGF-1, IGFBP-3, and several adipokines related to obesity and cancer were examined in the serum of the mice 10 weeks after the last AOM injection." (PMID 24732966, 2014). "During exercise, the AUC for serum total IGF‐1 response was 4.7‐fold higher from 0 to 15 min and 5.7‐fold higher from 0 to 40 min in participants without obesity compared to those with obesity." (PMID 40574473, 2025). "The integration of metabolomics and network pharmacology has identified six hub targets, namely AKT1, EGFR, ESR1, STAT3, IGF1, and MAPK1, that may be critical for the effects of EGCG on obesity-related precocious puberty." (PMID 40807299, 2025). "We investigated how obesity impacts the response of circulating insulin‐like growth factor‐1 (IGF‐1) to a single bout of endurance exercise in humans with and without obesity." (PMID 40574473, 2025). "IGF-1 can serve as a potential biomarker for Cushing’s disease, and hyperinsulinemia is not related to obesity." (PMID 40901060, 2025). "However, these correlations were statistically significant only within the subgroup of participants with obesity, possibly indicating a tighter regulation of IGF‐1 and IGFBP‐3 responses in the metabolic context of obesity." (PMID 40574473, 2025). "However, some proteins were primarily affected by other factors: SHBG by age and obesity; PRG4 by obesity; and IGF1 and RBP4 by age." (PMID 39972214, 2025). "Cafeteria diet induced significant obesity (mean weight 426.76 g vs. 263.09 g controls, p < 0.001) and increased leptin levels without altering insulin, IGF-1, or inflammatory markers." (PMID 40806434, 2025). "Because the production of both IGF‐1 and IGFBP‐3 occurs primarily in the liver, our findings suggest the presence of shared hepatic mechanisms that inhibit the secretion of both IGF‐1 and IGFBP‐3 in response to exercise in individuals with obesity." (PMID 40574473, 2025). "The HOMA‐IR did not significantly correlate (p > 0.05) with circulating total or free IGF‐1 responses, either across all participants or within the subgroups of participants with and without obesity." (PMID 40574473, 2025).
Obesity (continued). "Obesity-induced hyperinsulinemia increases the bioavailability of IGF-1 by reducing the levels of its binding proteins (IGFBP-1 and IGFBP-2), thereby enhancing IGF-1’s mitogenic and anti-apoptotic effects." (PMID 40722646, 2025). "The effect of obesity on the interplay between insulin, IGF-1, IGF binding proteins and growth hormone is complex and not fully understood, neither in human nor in veterinary medicine." (PMID 40001060, 2025). "IGF-1 and IGF-2 mediate the functions of insulin as well as the obesity process." (PMID 39104813, 2024). "It is known that excessive food intake and obesity activate mTOR through PI3K/Akt, IGF-1, and AMPK." (PMID 39339816, 2024). "However, there is a paucity of literature about the clinical relevance of the MEG3/miR-27a/IGF1 and MEG3/miR-181a/SIRT1 co-expression networks in predicting obesity-related CRC." (PMID 38704452, 2024). "The correlation analysis revealed a positive correlation of apoptotic factors Bad, Bak, and Bax, anti-apoptotic factors Bcl-2 and Bcl-XL, PKC-δ, inflammatory mediators AKT and NF-κB, IGF-1, proliferation marker Ki-67, and regulators of apoptosis cIAP2 and FLIP with obesity." (PMID 39395071, 2024). "EGCG may contribute to preventing obesity-related precocious puberty through targets such as AKT1, EGFR, ESR1, STAT3, IGF1, and MAPK1 and multiple signaling pathways, including the estrogen, PI3K-Akt, MAPK, and Jak-STAT pathways." (PMID 37334310, 2023). "While some studies have shown no alterations in IGF-1 levels in obesity, others have indicated a decrease in IGF-1 levels in the presence of obesity; others have also demonstrated an increase in IGF-1 levels in obese individuals." (PMID 37298507, 2023). "The safety and efficacy of GH and IGF-1 as a treatment for obesity are not clear, and long-term studies have not been conducted." (PMID 37298507, 2023). "In summary, EGCG may serve a role in preventing obesity-related precocious puberty through targets such as AKT1, EGFR, ESR1, STAT3, IGF1, and MAPK1 that acted on multiple signaling pathways, including the estrogen, PI3K-Akt, MAPK, and Jak-STAT pathways." (PMID 37334310, 2023). "Obesity exerts a multitude of effects both locally and systematically, through a series of inflammatory mediators (increased leptin, reduced adiponectin, TNF-α, IL-6), growth factors (insulin, IGF-1), and metabolism molecules (visfatin, grehlin, and resistin)." (PMID 37834153, 2023). "In PDAC, both insulin and IGF-1 are considered to play a role in cancer development and progression, with the PI3K and MAPK signaling pathways as its central pathways, and these signals are enhanced in obesity." (PMID 36755926, 2023). "Insulin-like growth factor 1 (IGF1) acts on orexin neurons from the lateral hypothalamus and exhibits anxiolytic properties, modulates coping behavior, reduces vulnerability to stress, but also promotes obesity due to stimulation of cell proliferation." (PMID 37374323, 2023). "According to the results of integrated metabolomics and network pharmacology, 6 hub targets, including AKT1, EGFR, ESR1, STAT3, IGF1, and MAPK1, may play significant roles in the effects of EGCG on obesity-related precocious puberty." (PMID 37334310, 2023). "The integrated metabolomics and network pharmacology indicated that AKT1, EGFR, ESR1, STAT3, IGF1, and MAPK1 may be key targets for EGCG in preventing obesity-related precocious puberty." (PMID 37334310, 2023). "Obesity-related inflammation and IR can also promote the conversion of HCC cells to the glycolytic pathway through upregulation of the different growth factors (insulin, IGF1) and ROS." (PMID 37266440, 2023). "Noteworthy, the first model provided by Rulex®® including IGF-1, was predictive of the presence/absence of metabolically healthy obesity with a precision of 66.67% and 72.15%, respectively." (PMID 35057554, 2022).
Obesity (continued). "So, the present study has demonstrated that combined training not only reduced the increased plasma levels of IGF-1 in non-obese, overweight, and obesity I women but also reduced pulmonary IGF-1, as demonstrated in breath condensate." (PMID 36160852, 2022). "Interestingly, gene expression dynamics of GHR, IGF-1 and IGFBP-3 was diminished in children with overweight/obesity compared to lean children." (PMID 36384443, 2022). "This relationship suggests that IGF-1 levels may be responsible for IVS thickening even in the presence of diabetes, hypertension, obesity, and other diseases known to affect the heart structure and function." (PMID 36568107, 2022). "We found that circulating GHBP, and in prepubertal children also IGF-1 but not IGFBP-3 are increased in children with overweight/obesity independently from age and sex." (PMID 36384443, 2022). "However, it must be considered that children with overweight/obesity have an increased AT mass and a higher number of adipocytes expressing GHR and IGF-1." (PMID 36384443, 2022). "This indicates that both obesity and OSAHS may lead to decreased IGF-1 levels in vivo, which aligns with the findings of previous research." (PMID 36120463, 2022). "We found that IGF-1 levels are associated with the risk of IVS thickening in patients with or without diabetes, hypertension, and obesity in a stratified analysis." (PMID 36568107, 2022). "We conclude that obesity-related elevations in serum GHBP and IGF-1 are unlikely to be caused by increased AT mass and elevations in GHBP are more closely related to liver status in children." (PMID 36384443, 2022). "Furthermore, we assessed if gene expression of GHR, IGF-1 and IGFBP-3 in AT cells is related to overweight/obesity and AT function." (PMID 36384443, 2022). "As children with overweight/obesity showed reduced gene expression of GHR, IGF-1 and IGFBP-3 in subcutaneous adipocytes and SVF cells, we next analysed if local expression of these factors in adipocytes and SVF cells was associated with parameters of AT function." (PMID 36384443, 2022). "Our study suggests that adipokines such as pro-enkephalin, IGF-1, chemerin, AGF, AFABP and leptin may affect obesity by directly controlling eating behavior (expressed as disinhibition, cognitive restraint and hunger)." (PMID 34636987, 2022). "Our study suggests that adipokines such as PENK, IGF-1, chemerin, AGF, AFABP and leptin might affect the development of obesity by directly modifying individual eating behavior." (PMID 34636987, 2022). "Gene transcription analysis showed the induction of Igf1 and reduction in IL6 and Tnf gene expression, supporting the hypothesis that obesity triggers a switch to a macrophage reparative state, probably in response to increased β-cell death." (PMID 33578952, 2021). "Limited human in vivo data have identified subtle disturbances in the growth hormone-IGF-1 axis in women with PCOS, however studies to date have not elucidated if these changes are linked to hyperinsulinemia, obesity or androgen excess." (PMID 33816477, 2021). "In this study, breast milk IGF-1 levels were not significantly different in mothers with obesity and mothers with normal weight." (PMID 34348809, 2021). "However, this reduced enteroid formation was reversed by insulin and IGF1, proposing that insulin/IGF-1 signaling mediates stemness acquisition of ISC in HFD-induced obesity." (PMID 33827616, 2021). "Our data suggested that the assessment of IGF-1, performing OGTT experiments, and calculating WBISI might provide useful clinical information on the severity and complications of obesity in children." (PMID 34485526, 2021). "Most studies report that free IGF1 levels increase in obesity as found here, but we found only a partial normalization in the HFDCH groups of both sexes." (PMID 34975768, 2021).
Obesity (continued). "Moreover, aberrant insulin/insulin-like growth factor-1 (IGF-1) signaling, which has a long-standing role in cancer, is activated by hyperglycemia or obesity and is believed to be an essential mediator of the oncogenic effects of these metabolic disorders." (PMID 32596159, 2020). "Translational studies evaluating the molecular phenotype of AI related to relevant signaling cascades in IGF-1 and MAPK pathways might also provide further insights into this potential bidirectional relationship between obesity and AIs." (PMID 32736549, 2020). "In contrast to total circulating IGF-1, most of which exists in complexes with IGFBPs, the actual bioavailability of IGF-1 at a tissue level in vivo is difficult to determine, which complicates the contribution of IGF-1 to the relationship between obesity and cancer." (PMID 33604295, 2020). "Administration of a low IGF-1 dose inhibits the somatotroph response to GH-releasing hormone in obese and normal subjects, indicating that somatotroph sensitivity to the inhibitory effect of IGF-1 is conserved in obesity." (PMID 32806629, 2020). "However, obesity is known to result in impaired IGF-1 signaling, and circulating IGF-1 levels have been shown to be dysregulated in obesity." (PMID 32824483, 2020). "In particular, total IGF-1 concentrations did not seem to be significantly increased in obesity, whilst the amount of free IGF-1 relative to total IGF-1 was increased." (PMID 33101407, 2020). "The course of this specific phase of puberty has not been related to the obesity, high androgens’ levels nor advanced bone age as well as the rhGH dose or IGF1 levels." (PMID 33050529, 2020). "The contribution of IGF-1 to the obesity-cancer link is not simple, as the positive relationship between IGF-1 levels and BMI exists only up to 27 kg/m2 and becomes negative thereafter, secondary to hyperinsulinemia inhibiting growth hormone secretion." (PMID 33604295, 2020). "Baseline IGF-1 SDS did not significantly differ according to obesity status in the IGHD and OGHD groups." (PMID 31700044, 2019). "Our observation that systemic and local IGF-1 levels were increased in ad libitum HFD-fed, but not R-HFD-fed, mice reveals the importance of excess calories rather than lipids in the regulation of IGF-1 in obesity." (PMID 31003943, 2019). "We previously demonstrated that 8 weeks HF led to blunting of both insulin and IGF-1-mediated vasorelaxation of the aorta;2 however, this study did not examine the effect of obesity on resistance vessel function." (PMID 30295509, 2019). "We cultured HUVECs in conditions aiming to recapitulate different components of the obesity phenotype including elevated: insulin, IGF-1, glucose with and without insulin, angiotensin II, hydrogen peroxide and TNF-α for 24 h." (PMID 30295509, 2019). "The biological processes “Platelet degranulation,” “Positive regulation of glucose import” and “Cellular response to insulin stimulus,” already found modulated in obesity (PDGFB, SERPING1 ADIPOQ, PIK3R1, IGF1) were further enriched in ObCRC with respect to Ob individuals." (PMID 30838002, 2019). "Human observational studies have reported increased cancer mortality in those with obesity and T2DM, which may be at least in part explained by hyperinsulinemia, elevated insulin-like growth factor-1 (IGF-1), or potentially both." (PMID 29402900, 2018). "Increasing prevalence of obesity is thought to contribute to the increasing incidence of RCC via several hormonal mechanisms including free estrogen, insulin and IGF-1, as well as physical damage mechanisms by lipid peroxidation, higher glomerular filtration rate and renal plasma flow." (PMID 29568408, 2018). "The objectives of this study were to investigate the effects of obesity and DHEA feeding on liver steatosis, body weight gain, and serum DHEA, DHEA sulfate (DHEA-S), insulin-like growth factor-1 (IGF-1), and insulin-like growth factor binding protein-3 (IGFBP-3) levels." (PMID 28335515, 2017).
Obesity (continued). "Expression of IGF-1 and LEPR indicates a relevant role in androgenic features reversion present in PCOS, hormonal equilibrium, body weight regulation, and glucose metabolism, therefore, under phenotype obesity and infertility regulation in this model." (PMID 29430464, 2017). "The result is consistent with those of a previously epidemiological study based on 3328 subjects (aged 19–72 years) which reported a similar negative correlation between IGF-1 and obesity-related anthropometric markers in both men and women." (PMID 27343122, 2016). "As markers of late osteogenesis, the lack of COLA1a and IGF-1 in obASCs during late osteogenesis would suggest that obesity has altered osteogenic differentiation of these cells mechanistically." (PMID 26818763, 2016). "The physiological link between an obesity-related low IGF-1 level and the presence of renal lesions is not completely understood; however, it is widely accepted that kidney disease influences the IGF/GH axis." (PMID 27138941, 2016). "Our principal aim was to compare the serum IGF-1 concentrations in morbidly obese patients with normal renal function with or without early obesity-related glomerular lesions." (PMID 27138941, 2016). "DM2 and obesity may promote PDAC through pro-tumorigenic insulin and insulin-like growth factor-1 (IGF-1) as well as chronic inflammation." (PMID 26641266, 2015). "While the pathophysiology linking obesity to IGF-1 and IGFBP-3 levels are not completely resolved, data show that increases in visceral fat are associated with elevated levels of serum free fatty acids in the blood." (PMID 26352264, 2015). "In the hyperinsulinemic state (as commonly occurs with obesity), higher insulin levels in the portal circulation in response to hyperglycemia upregulate the growth hormone receptor (GHR) and augment GHR signaling, increasing hepatic IGF-1 production." (PMID 24280167, 2013). "Some studies have shown that there are lower serum IGF-1 concentrations in obesity possibly due to the negative feedback that the initial rise in serum IGF-1 has on the production of growth hormone (GH) by the pituitary gland." (PMID 23983688, 2013). "Despite reports of various effects of obesity on IGFBP3, C-peptide and IGF-1, BMI was not independently associated with cancer outcomes once the effect of serum C-peptide was adjusted." (PMID 23405181, 2013). "The use of somatostatin vaccines for treatment of obesity is based upon previous studies using GH therapy and the accepted endocrine model of somatostatin to down-regulate growth hormone releasing hormone (GHRH), GH and IGF-1." (PMID 22958753, 2012). "In our case series, at baseline the activity of the GH-insulin-like growth factor-1 (IGF-1) system was impaired with low GH values, low total IGF-1 and in relation to the obesity low levels of free IGF-1 and non-suppressed IGF-binding-protein-1 (IGFBP-1)." (PMID 19128470, 2009). "In control participants without obesity, serum total IGF‐1 and IGFBP‐3 levels increased in parallel in response to exercise, rising well above pre‐exercise values at both 15 and 40 min into the exercise session, and returning to baseline within 15 min after exercise ended." (PMID 40574473, 2025). "Similarly, obesity-driven metabolic dysregulation disrupts the secretion of neuroprotective factors such as brain-derived neurotrophic factor (BDNF) and insulin-like growth factor 1 (IGF-1), reducing neuronal viability and limiting neurorepair capacity." (PMID 40332538, 2025). "However, a concurrent attenuation in serum IGFBP‐3 response, which regulates free (i.e., biologically active) IGF‐1 in circulation, results in no change in circulating free IGF‐1 levels during endurance exercise in individuals with obesity." (PMID 40574473, 2025). "Therefore, the primary goal of this study was to compare circulating concentrations of IGF‐1 and its binding proteins at rest, during an acute bout of endurance exercise, and immediately afterward in adults with and without obesity." (PMID 40574473, 2025).